PXDN (peroxidasin)
Diseases named in the same sentence as PXDN in open-access papers (continued):
Sharing a sentence is not in itself a finding about the gene and the disease.
tumor (continued). "Furthermore, we discussed the effects of PXDN on the tumor microenvironment, including the infiltration of fibroblasts and immune cells." (PMID 35982948, 2022). "Our results provide a comprehensive understanding of the carcinogenicity of PXDN in different tumors and suggest that PXDN may be a potential target for tumor immunotherapy, providing a new candidate that could improve cancer clinical diagnosis and treatment." (PMID 35982948, 2022). "To clarify the differential expression of PXDN in tumor tissues versus normal tissues in different tumors, we combined the PXDN expression profile data of all samples obtained from the TCGA database with those of GTEx data to explore the difference of PXDN mRNA expression." (PMID 35982948, 2022). "Additionally, for the first time, the relationship of PXDN with the tumor microenvironment and infiltration of fibroblasts and different immune cells within different tumors was explored, and the possible molecular mechanism of the effect was also discussed." (PMID 35982948, 2022). "We continued to explore the relationship between PXDN and the tumor microenvironment." (PMID 35982948, 2022). "Together, our results indicate that PXDN acts as a tumor-promoting factor in OSCC." (PMID 32751434, 2020). "Therefore, we hypothesized that PXDN might affect tumor metastasis and host immunity, which requires further verification." (PMID 39399179, 2024). "A systematic pan-cancer analysis provides a comprehensive understanding of the carcinogenicity of PXDN and suggests that it may be a potential target for tumor immunotherapy, providing a new candidate that could improve the clinical diagnosis and treatment of cancer." (PMID 39399179, 2024). "However, a role for PXDN in tumour angiogenesis has yet to be investigated." (PMID 37801286, 2023). "There is evidence to suggest that PXDN may influence tumour sensitivity to therapies." (PMID 37801286, 2023). "Therefore, PXDN may be expressed in tumour regions undergoing EMT although the biological mechanisms underpinning this remain to be elucidated." (PMID 37801286, 2023). "Pretreatment using PXDN inhibitor could alleviate the tumor-promoting effect of FPM." (PMID 35437145, 2022). "Furthermore, four tumors showed PXDN-positive fibrils in the tumor stroma." (PMID 34964086, 2021). "PKM2 activation status may be an indicator of tumor-promoting PXDN function." (PMID 32751434, 2020). "Peroxidasin (PXDN), a secreted peroxidase that catalyzes collagen cross-linking in the ECM, has emerged as a potential mediator of tumor progression." (PMID 41413560, 2025). "Taken together, our findings demonstrate that PXDN drives EMT and tumor progression in NPC through activation of the PI3K/AKT signaling axis." (PMID 41413560, 2025). "Four of the top five most up-regulated glycoproteins in tumour ECM – thrombospondin-1 and -2, SPARC and peroxidasin – formed a connected subnetwork, pointing to their common functional roles in organising the collagen ECM and regulating cell–ECM adhesion." (PMID 37397358, 2023). "In tumours, peroxidasin and ADAMTS16 were found variably distributed between tumour stroma and tumour cells." (PMID 37397358, 2023). "The PXDN expression was also positively correlated with macrophage and neutrophil infiltration, but negatively correlated with CD8+ T cells, which are tumor-killing cells." (PMID 35982948, 2022). "Despite this variability, PXDN was uniformly correlated with an invasive phenotype in all models examined, underscoring its non-redundant role in promoting tumour aggression." (PMID 41413560, 2025). "IHC analyses determined that both peroxidasin and ADAMTS16 were enriched in tumour cell-rich regions of lung tumour tissue, although IHC scoring of either of these candidates did not represent a significant predictor of survival in the TMA cohort of NSCLC patients." (PMID 37397358, 2023).
tumor (continued). "Blv-miR-B4-3p shares seed sequence similarities with the host miRNA miR-29a, which is known to downregulate the expression of two tumor suppressor genes, the genes coding for the HMG-box transcription factor 1 (HBP1) and for the peroxidasin homolog (PXDN), in B-cell tumors." (PMID 37268923, 2023). "Notably, tumor ECs were featured by upregulation of angiogenesis-related genes including collagens (e.g., COL4A1, COL4A2), PXDN, SPARC and HSPG2, as well as proliferation markers (e.g., MKI67, TOP2A)." (PMID 36138435, 2022). "Additionally, genes like COL4A1, PLOD2, and PXDN, which participate in extracellular matrix remodeling, alongside immune-related genes such as CYFIP2, EMP3, and HLA-B, are instrumental in modulating the tumor microenvironment and facilitating immune evasion." (PMID 39949776, 2025). "Given that PXDN mediated cross-linking of collagen IV is an essential process in basement membrane generation and repair, inhibition of this process outside of the tumour microenvironment may have negative effects." (PMID 37801286, 2023). "However, the role and specific mechanism of PXDN in tumor are unclear, and no systematic pan-cancer studies on PXDN have been reported to date." (PMID 35982948, 2022). "Genes encoding collagens (COL4A1, COL4A2), collagen-modifying enzyme (PXDN), and other components of the basement membrane (LAMB1, HSPG2) also ranked in the top 10 most enriched Co1 EC markers, indicating that extensive matrix remodeling occurs in GBM during tumor angiogenesis." (PMID 34228647, 2021). "Another protein that was significantly upregulated following PXDN knockdown was protein tyrosine phosphatase type IVA 2/ phosphatase of regenerating liver (PTP4A2/PRL-2); this is a prenylated protein tyrosine phosphatase with oncogenic activity that has been proposed to drive tumor metastasis." (PMID 31234468, 2019). "The most enriched glycoproteins in tumour ECM compared to non-tumour ECM included thrombospondin-2 (16.9-fold), MXRA5 (14.4-fold), peroxidasin (2.5-fold), thrombospondin-1 (2.5-fold), SPARC (2.3-fold), FRAS1 (2.3-fold) and tenascin-C (2.1-fold)." (PMID 37397358, 2023).
cancer (24 papers, 2010 to 2026). A tumor composed of atypical neoplastic, often pleomorphic cells that invade other tissues. "Studies have shown that PXDN is highly expressed in cancer cells undergoing EMT, a process that underlies metastatic dissemination and poor prognosis of patients." (PMID 41413560, 2025). "Comprehensive analysis revealed that upregulation of PXDN is associated with worse clinical prognosis in various human cancers." (PMID 39399179, 2024). "Peroxidasin promotes cancer cell invasion, angiogenesis, and has been associated with increased metastasis." (PMID 37801286, 2023). "Although PXDN has been linked to fibrosis and cancer in some organs there is limited information on its role in development, including in the breast." (PMID 34964086, 2021). "Similarly, PXDN, previously reported as a pan-cancer biomarker and linked to ocular disorders, was also downregulated in our analysis." (PMID 40574839, 2025). "In this mini-review, we discuss the known and emerging roles of PXDN in cancer progression, the known associations between PXDN expression and patient outcome, and examine the literature surrounding PXDN regulatory pathways and the implications of these in cancer progression." (PMID 37801286, 2023). "The most common type of mutations of the PXDN gene in cancers are missense mutations, however the pathology of many of these, including potential effects on enzymatic activity, if any, remains unknown." (PMID 37801286, 2023). "Peroxidasin (PXDN), an extracellular matrix (ECM)-associated peroxidase, has been implicated in cancer progression." (PMID 41601454, 2026). "We also uncovered new oncogenic roles for PXDN in promoting cancer progression and regulating T-cell immunosuppressive function in NPC." (PMID 39399179, 2024). "Our results demonstrate that elevated PXDN levels can distinguish cancer from normal individuals and predict poor survival in cancer patients." (PMID 39399179, 2024). "In this study, we investigated the expression of PXDN in various cancers and found that it is highly expressed and serves as a pan-cancer biomarker." (PMID 39399179, 2024). "In conclusion, we have characterized PXDN as a valuable biomarker for pan-cancer diagnosis and prognosis." (PMID 39399179, 2024). "The present study investigated the expression profile of PXDN in various cancer types and uncovered new roles for PXDN in promoting cancer progression." (PMID 39399179, 2024). "The high PXDN expression level has been considered a signature of drug resistance in cancer cells, and it was suggested that patients with a high PXDN expression are more likely to develop drug resistance." (PMID 38968283, 2024). "In this study, we conducted an in-depth analysis of PXDN expression in cancer using several databases, including TCGA, GTEx, CPTAC, and GEO." (PMID 39399179, 2024). "We also uncovered new oncogenic roles for PXDN in promoting cancer progression and regulating T-cell immunosuppressive function." (PMID 39399179, 2024). "Further research is required to better understand the molecular mechanisms of peroxidasin in cancer progression, as well as downstream signalling pathways and interacting partners of peroxidasin." (PMID 37801286, 2023). "A range of transcriptional regulatory pathways of PXDN expression have been identified in different cancer cells, including methylation, transcription factors and microRNAs." (PMID 37801286, 2023). "PXDN is upregulated in tissue fibrosis and contributes to the progression of numerous types of cancer." (PMID 38275643, 2023). "This review highlights the current literature exploring the known roles of peroxidasin in normal tissues and cancer progression, regulators of peroxidasin expression, and the reported relationships between peroxidasin expression and patient outcome in cancer." (PMID 37801286, 2023).
cancer (continued). "A better understanding of the cancer-specific alterations in PXDN expression and activity, the downstream effects of collagen IV cross-linking, and role this plays in disease progression is needed." (PMID 37801286, 2023). "PXDN represents an interesting therapeutic target for inhibition, as it plays a role in numerous pathologies, including cardiovascular disease, cancer and fibrosis." (PMID 38275643, 2023). "PXDN is highly expressed in cancer cells undergoing epithelial to mesenchymal transition (EMT), a process which underpins metastatic dissemination and poor patient outcomes." (PMID 37801286, 2023). "Systematic pan-cancer analysis of PXDN using data from TCGA, GTEx, and related databases to compare PXDN expression with clinical characteristics." (PMID 37801286, 2023). "PXDN knockdown reduced proliferation, migration and invasion of cancer cells, as well as reduced PI3K and AKT phosphorylation." (PMID 37801286, 2023). "Whilst peroxidasin is reported to be up-regulated in a number of different cancers, the role that it plays in disease progression and metastasis has only recently begun to be studied." (PMID 37801286, 2023). "Although there are many unanswered questions about the Warburg effect in cancer, these results suggest that the Warburg effect induced by PXDN is cancer-promoting." (PMID 35330413, 2022). "The results indicated that PXDN mainly regulates GBM development by activating cancer hallmarks, including fatty acid metabolism, epithelial-mesenchymal transition, inflammatory response, glycolysis, hypoxia and Wnt/beta-catenin signaling pathway." (PMID 36118855, 2022). "This study employed data from multiple databases, including The Cancer Genome Atlas and The Genotype-Tissue Expression, to conduct a specific pan-cancer analysis of the effects of PXDN expression on cancer prognosis." (PMID 35982948, 2022). "In cancer cells, interaction between PXDN and HO-1 promotes invasion by attenuating expression of the ECM proteins fibronectin and laminin." (PMID 32751434, 2020). "Co-expression of PXDN and heme oxigenase-1 (HO-1) promotes the proliferation and invasion of cancer cells." (PMID 32751434, 2020). "PXDN is overexpressed in several cancers including ovarian, bladder and esophageal cancer and has been associated with metastatic melanoma and brain tumors." (PMID 31234468, 2019). "Immunofluorescence and Western blotting confirmed the positive correlation of expression of PXDN and HO-1 in BeWo cancer cells as well as co-localization of these two proteins in invasive extravillous trophoblast cells." (PMID 20667089, 2010). "To explore whether PXDN could be a prognostic marker in different tumors, we divided cancer cases into high- and low-expression groups according to PXDN expression levels in the TCGA dataset." (PMID 39399179, 2024). "We characterized PXDN as a valuable biomarker for pan-cancer diagnosis and prognosis." (PMID 39399179, 2024). "PXDN is a valuable biomarker for the diagnosis and prognosis of cancer." (PMID 39399179, 2024). "However, PXDN has also been shown to be highly expressed by cancer cells in various cancers, as well as by some fibroblasts especially during tissue fibrosis." (PMID 37801286, 2023). "PXDN regulation in cancer may also be a result of dysregulation of Snai1, a transcriptional repressor." (PMID 37801286, 2023). "There are limited studies examining the source of expression of PXDN in cancer." (PMID 37801286, 2023). "The exact role that PXDN plays in the progression of different cancers remains unclear and is likely multifaceted." (PMID 37801286, 2023). "In this context, inhibitors targeting MPO, EPO and PXDN may have favourable outcomes for treating cancer compared with targeting single peroxidase enzymes alone." (PMID 37801286, 2023).
cancer (continued). "Ultimately, more research is needed to understanding the exact role that PXDN plays in different cancer types and how this is regulated before researchers and pharmaceutical companies consider PXDN to be an economically viable target for the development of targeted therapies." (PMID 37801286, 2023). "Given that cellular energetics are often altered in cancer cells, future studies could examine the link between glucose metabolism, autophagic flux, oxidative stress and PXDN in the cancer setting." (PMID 37801286, 2023). "Whilst investigation into the role of PXDN on intracellular signalling in cancer is limited, research in non-transformed cells has implicated PXDN in the regulation of key signalling networks." (PMID 37801286, 2023). "Our results also show that PXDN tends to play a pro-cancer role in tumors." (PMID 35982948, 2022). "Consistently, functional enrichment analysis revealed that several cancer hallmarks were enriched in the GBM cases with high PXDN expression, such as epithelial-mesenchymal transition (EMT), fatty acid metabolism, glycolysis, hypoxia, inflammatory response, and Wnt/beta-catenin signaling pathway." (PMID 36118855, 2022). "Moreover, PXDN was bound up with several classic cancer pathways including PI3K/Akt pathway, Hippo signaling and Wnt pathway." (PMID 36118855, 2022). "Further study is required to determine the mechanism of PXDN action during the EMT in cancer cells." (PMID 32751434, 2020). "The detailed role of mitochondria in the action of PXDN in cancer requires further study." (PMID 32751434, 2020). "PXDN has been reported to promote cancer invasion when co-expressed with HO-1." (PMID 32751434, 2020). "This may imply that PXDN inhibits neurite extensions which needs to be further explored, whether this may play a role in processes such as neuroendocrine differentiation of cancer cells." (PMID 31234468, 2019). "We conclude that PXDN could serve as a pan-cancer biomarker." (PMID 39399179, 2024). "The increased expression of PXDN in many cancers, as well as its links to increased cell proliferation, migration, invasion, and metastasis, suggest that it may be a viable candidate for therapeutic targeting in cancer." (PMID 37801286, 2023). "Alternately, some studies have hypothesised that PXDN's use of hydrogen peroxide to catalyse the formation of HOBr, both of which are forms of reactive oxygen species (ROS), may be altering the levels of oxidative stress experienced by cancer cells." (PMID 37801286, 2023). "PXDN effects on cells are most likely through its collagen IV cross-linking activity, yet there is evidence to suggest that PXDN may have additional functions relevant to the cancer setting." (PMID 37801286, 2023). "PXDN may also play a role in modulating PI3K/Akt signalling in cancer." (PMID 37801286, 2023). "PXDN may contribute to cancer progression by regulating ROS production to low levels." (PMID 35330413, 2022). "This may imply that immunotherapy will not be favorable when PXDN is highly expressed, and it may be one of the mechanisms associated with the pro-cancer role of PXDN in most tumors." (PMID 35982948, 2022). "PXDN may contribute to cancer progression by adjusting the production of ROS to low concentrations." (PMID 32751434, 2020). "Together, these results suggest that PXDN might promote OSCC by affecting cancer cell metabolism." (PMID 32751434, 2020). "We demonstrate that PXDN regulates CAF behavior, with subsequent matrix remodeling affecting cancer cell behavior." (PMID 42291185, 2026). "Here, we establish PXDN as an upstream activator of the PI3K/AKT pathway in NPC, a central signaling axis controlling core cancer hallmarks." (PMID 41413560, 2025).
cancer (continued). "Mentioning the PXDN gene’s expression, which with an increased level in the HG-ESS, was unevenly expressed in 13 cancers." (PMID 38167455, 2024). "Mechanistically, PXDN promotes ECM signaling and potentially suppresses T-cell infiltration and activation, thereby facilitating cancer progression." (PMID 39399179, 2024). "Mechanistically, PXDN activates extracellular matrix (ECM) signaling pathways while simultaneously inhibiting T-cell infiltration and activation, thereby facilitating cancer progression." (PMID 39399179, 2024). "We explored the biological function of PXDN in NPC and found that PXDN overexpression promoted cancer cell proliferation and invasion." (PMID 39399179, 2024). "PXDN (peroxidasin) is involved in the formation and stabilization of the ECM and has been detected in several types of cancer." (PMID 32536039, 2020). "Another upregulated protein following PXDN knock-down, Aldehyde dehydrogenase 1 (ALDH1) is a marker of stem cells and cancer stem cells, and it acts as a detoxifying enzyme that oxidizes aldehyde into carboxylic acid and converts retinol into retinoic acid." (PMID 31234468, 2019). "PXDN catalyzes H2O2-driven oxidation and therefore usurps H2O2, yet ROS is generally higher in cancer." (PMID 31234468, 2019). "In addition, ERFE was co-expressed with the genes involved in extracellular matrix (ECM) deposition and remodeling, including PXDN, COL4A1, and LOXL2 that are known to promote cancer invasion and metastasis." (PMID 36675239, 2023). "Although PXDN overexpression correlates with poor prognosis in several carcinomas, and its prognostic value in NPC has been recently documented, the functional mechanisms through which PXDN promotes aggressiveness, and the regulatory basis for its overexpression in NPC, remain largely unknown." (PMID 41413560, 2025).
cardiovascular disease (9 papers, 2021 to 2025). "PXDN is reported to play essential roles in several cardiovascular diseases via catalyzing hydrogen peroxide to form hypochlorous acid and augment oxidative stress." (PMID 33903591, 2021). "Peroxidasin (PXDN) is a heme-containing peroxidase that augments oxidative stress and plays an essential role in cardiovascular diseases, while whether PXDN contributes to the pathogenesis of DCM remains unknown." (PMID 33903591, 2021).